FOXP3 (forkhead box P3)
Diseases named in the same sentence as FOXP3 in open-access papers (continued):
Sharing a sentence is not in itself a finding about the gene and the disease.
tumor (continued). "Patients (Groups III and IV) whose tumours underwent a poor pathological response showed no significant change in the circulating levels of FOXP3+ Tregs, compared with pre-treatment levels." (PMID 23320561, 2013). "Although most available evidence indicates that the bulk of tumor-infiltrating Foxp3+ Tregs are tTreg, this does not preclude a significant immunosuppressive role for pTreg or indeed Foxp3− cells." (PMID 23874342, 2013). "Indeed, FOXP3 has been shown to be expressed, albeit transiently, in activated CD8+ T cells, in tonsillar suppressive CD8+ T cells, and even in tumor cells." (PMID 22471961, 2012). "In addition, we demonstrated a correlation both between tumor infiltrating CD8+ and Foxp3+ T-cells to HPV status in TSCC." (PMID 22701698, 2012). "We therefore compared the number of tumor infiltrating high avidity T cells to the number of CD4+Foxp3+ Tregs in the tumor of vaccinated mice with and without Cy treatment." (PMID 22359647, 2012). "Moreover, in many tumor entities, the recruitment of thymus-derived “natural” CD4+CD25+FoxP3+ regulatory T cells (nTregs) contributes to the immunosuppressive status." (PMID 22674057, 2012). "There were no changes in FoxP3+CD4CD25+ T cells in the tumor site and periphery following MDSC depletion with anti-Gr1 or anti Ly6G treatment (data not shown)." (PMID 22815789, 2012). "In addition, the tumours that developed in mice implanted with both HCC cells and HSCs contained more Foxp3-positive cells." (PMID 22641338, 2012). "Genetic marking of current and ex-FoxP3+ T cells revealed that tumor-infiltrating FoxP3+ T cells are highly stable and do not readily convert back to FoxP3− T cells." (PMID 22292042, 2012). "In preclinical studies, depletion of FoxP3+Tregs in mice early in tumor progression enabled immune rejection whereas no therapeutic effect was seen with established tumors." (PMID 22879926, 2012). "Inhibiting STAT3 activity reduces conversion of Foxp3-negative T cells to tumor-associated Tregs and increases CD8+ T cell infiltration in tumor - a strategy that has been used to inhibit primary tumor growth." (PMID 22911830, 2012). "The use of Foxp3 reporter mice, including DEREG mice have firmly established the crucial and non-redundant role of CD4+Foxp3+ Tregs in preserving the immune homeostasis and maintaining immunological self/tumor-specific tolerance." (PMID 22957107, 2012). "Stimulation with aAPC/mOKT3 did not expand Foxp3+ regulatory T cells, and expanded tumor infiltrating lymphocytes predominantly secreted Th1-type cytokines, interferon-γ and IL-2." (PMID 22279573, 2012). "Second, FTS induced an increase in regulatory T cells in mouse splenocytes, but the inhibitory effects of FTS on tumor growth were not affected by these Foxp3+ T lymphocytes." (PMID 22323550, 2012). "The effects of FTS-induced Ras inhibition on Foxp3 expression in tumor cells and its influence on their growth are not known." (PMID 22323550, 2012). "It should be taken into consideration that FOXP3 mRNA can be present without translation and a potential FOXP3 expression by tumor cells can severely influence the results." (PMID 24212779, 2011). "In our experiments, the decline in the number of Tregs, the increase in the ratio of CD8+ T cells to FoxP3+ CD25+ CD4+ Tregs and the lymphopenic environment after cyclophosphamide treatment favor enhanced priming of tumor-specific immune responses during vaccination." (PMID 21859450, 2011). "It has been proposed that both pre-existing naturally occurring Treg-cells (nTreg-cells) and adaptive Treg-cells (aTreg-cells) induced from non-Treg precursor cells contribute to the total pool of tumor-infiltrating FoxP3+ Treg-cells." (PMID 21559338, 2011). "In addition to FoxP3 and IDO, other proteins likely are involved in creating an anti-tumor immune microenvironment." (PMID 22123319, 2011).
tumor (continued). "The mean SPARC and FOXP3 expression in the primary tumours of patients with and without disease recurrence at each time point were measured to determine if the levels correlated with disease recurrence over time." (PMID 21818290, 2011). "In the multivariate model, tumour-infiltrating CD45RO+-cell density, but not CD3+, CD8+, or FOXP3+-cell density, was significantly associated with survival (P = 0.0032)." (PMID 22110523, 2011). "In contrast, regulatory/suppressor T cells (Treg), characterized ex vivo by high expression of the IL-2R α-chain (CD25) and of the lineage-specific transcription factor FOXP3 and low expression of the IL-7R α-chain (CD127), are believed to inhibit anti-tumor responses." (PMID 21829534, 2011). "Only a subset of tumor cells in anaplastic lymphoma kinase (ALK)+ ALCL expresses FOXP3, and the level of expression varies among tumor cells, pointing to an intricate mechanism of FOXP3 regulation." (PMID 22151904, 2011). "At various tumor volumes, tumor-infiltrating lymphocytes (TIL), splenocytes (SPL), and lymph node (LN) cells were isolated and CD8 and CD4 T cells analyzed by flow cytometry for percentage expression of Foxp3 (EGFP)." (PMID 22112546, 2011). "Consistent with the flow cytometric analysis, we observed that FoxP3+ cells preferentially accumulated in tumor tissue (7.3±0.6/hpf) rather than in non-tumor tissue (2.8±0.4/hpf) or normal control livers (0.4±0.1/hpf) (both P<0.001 for T vs. nT and T vs. NC)." (PMID 21935436, 2011). "Therefore, they treated DC with IL-15 and a p38 MAPK inhibitor and these cells are capable of inducing TNFα+ FoxP3- IL-17 secreting CD4+ T cells that show reduced PD-1 expression and tumor-specific CTL." (PMID 21226916, 2011). "A comparison of the numbers of CD25+Foxp3+ Tregs and CD3+Foxp3+ and CD8+Foxp3+ in TILs between oral SCCs and 15 human tumor-free tonsils again revealed an increased number of Tregs in carcinomas whereas no significant change was noted in the number of CD3+Foxp3+ and CD8+Foxp3+ in TILs." (PMID 21437225, 2010). "Since in our cases the tumour cells were consistently FoxP3-negative, this did not interfere with the interpretation of our results." (PMID 19698134, 2009). "The Foxp3 count was also analysed as a dichotomous variable using the median value to distinguish tumours with a low or negative Foxp3 count (⩽8.2) and tumours with a high Foxp3 count (>8.2)." (PMID 19935800, 2009). "In high-grade serous tumors from optimally debulked patients, positive associations were seen between intraepithelial cells expressing CD3, CD4, CD8, CD45RO, CD25, TIA-1, Granzyme B, FoxP3, CD20, and CD68, as well as expression of MHC class I and II by tumor cells." (PMID 19641607, 2009). "When administered from week 26 to week 32, rapamycin decreased tumor size by 50% but did not affect tumor multiplicity, and the number of tumor infiltrating Foxp3+ cells was not decreased (data not shown)." (PMID 19330036, 2009). "Tumour-infiltrating lymphocytes (CD4, CD8, Foxp3), mast cells (MCs) (tryptase and chymase), microvessel count (MVC) and VEGF were determined by immunohistochemistry in two series of MPM patients: 60 patients treated with intra-pleural preoperative IL-2 and 33 patients untreated." (PMID 19935800, 2009). "Foxp3 mRNA as well as Foxp3 protein was detected in all tumor cell lines, albeit in variable levels, not related to the tissue of origin." (PMID 18430198, 2008). "It seems that FOXP3, B7-H1 and PD-1 molecules co-expressed in the TIL of the same tumor tissues may have synergistic effect in weakening the immune response of patients." (PMID 18294387, 2008). "Employing an anti‐CCL20 neutralizing antibody and Foxp3DTR mice, it is demonstrated that CCR6+Foxp3+ regulatory T cells (Tregs) recruited by Gal1‐induced TAMs contributed to reduced infiltration and dysfunctional state of CD8+ T cells, subsequently facilitating tumor progression." (PMID 39853961, 2025).
tumor (continued). "However, tumoral Treg cells were uniquely sensitive to Foxp3 degradation, which led to impaired suppressive function and tumor growth restraint absent pronounced adverse effects." (PMID 40470210, 2025). "However, it is important to note that our study did not differentiate between FOXP3 staining in tumor cells and infiltrating immune cells." (PMID 40587482, 2025). "Notably, this balance shifts throughout tumor progression: early-stage NSCLC, characterized by low TGF-β and high IL-6, favors Th17 polarization, whereas advanced stages, enriched in TGF-β, promote Foxp3 expression and Treg dominance." (PMID 41181112, 2025). "The results showed that pretreatment with azacitidine followed by sequential combination with immunotherapeutic agents only significantly reduced the density of FoxP3+ regulatory T cells in the tumor microenvironment, without effectively enhancing the infiltration of effector T cells (CD8+ T cells)." (PMID 41335282, 2025). "The rising trend of FOXP3 mRNA expression from stage I–III observed in both our MMA and TCGA cohorts may reflect an intensified immune response, potentially due to increased infiltration of immune cells within the tumor environment." (PMID 40806346, 2025). "In mice, DP T cells showed an increased expression of Foxp3, exhibiting modest immunosuppressive features in vitro, while human DP T cells revealed a phenotype similar to that of classical cytotoxic CD8+ T cells, suggesting a potential capability of contributing to tumor eradication." (PMID 40422223, 2025). "In summary, our data suggest that targeting FoxP3 through small molecules may be a therapeutic strategy to inhibit Tregs in the TME and enhance anti-tumor responses potently, implying potential application in patients as a stand-alone treatment or in combination with other therapies." (PMID 40034859, 2025). "FOXP3 represents a malignant marker in non-cancerous and differentiated lymphocytes, such as Treg cells, that control and induce immunosuppressive properties in the tumor microenvironment." (PMID 40746879, 2025). "Tumor-resident CD8+ T cells, polarized by such a type 1 cytokine–rich environment, downregulate tumor-specific immune responses by facilitating the local migration of CD4+Foxp3+ Tregs through the accumulation of several CCR5-specific cytokines, such as MIP-1α (CCL3) and MIP-1β (CCL4)." (PMID 40553564, 2025). "On the other hand, BMI1 overexpression (27% of cases) showed paradoxically significant inverse correlation with FOXP3+ CD3+ TIL (p = 0.008), loss of p27 (p = 0.002), and the combined loss of p21/p27 expression (p = 0.006), tumor size (p = 0.003), and ER negative status (p = 0.049)." (PMID 40943144, 2025). "Indeed, studies indicate that FOXP3 expression correlates with reduced cytokine production and cytotoxicity, and recent findings suggest that TCR-induced FOXP3 expression in CD8+ T cells impairs their anti-tumor activity." (PMID 40955316, 2025). "The levels of tumor-infiltrating CD4+CD25+Foxp3+ Treg cells were not affected by p38 blockade." (PMID 41282257, 2025). "Finally, we examined the spatial distribution of key tumor microenvironment markers such as CD8A, PD-L1, FOXP3, CD163, and VEGFA, further confirming that TMErisk genes aggregate in the tumor center and recruit immune cells, forming an immune hub (Figures 6G1, G2, G3, G4, G5)." (PMID 40104502, 2025). "Furthermore, tumoral Treg cells were uniquely sensitive to Foxp3 degradation, which led to impairment in their suppressive function and tumor shrinkage in the absence of pronounced adverse effects." (PMID 41062655, 2025). "Despite no obvious change in the total CD4+ T cells with anti-VISTA or RT treatment alone, the FoxP3/CD4+ T cell ratio significantly decreased in the group treated with anti-VISTA alone, suggesting an impact on Treg differentiation or recruitment within the tumor." (PMID 40580480, 2025).
tumor (continued). "Furthermore, there was no apparent relationship between the extent of FOXP3 knockdown and tumor shrinkage (data not shown)." (PMID 39937271, 2025). "Tumor promoter exposure in these mice leads to elevated levels of C-X-C motif chemokine ligand 5 (CXCL5) and macrophage colony-stimulating factor (M-CSF), promoting the accumulation of CD200R+ MDSCs and forkhead box P3 (FoxP3+) regulatory T cells while reducing activated CD4+ T cells in the skin." (PMID 40868818, 2025). "We quantitatively assessed the infiltration of various tumor immune cells in the tumor center and invasive margins, including CD45+ leukocytes, CD3+ and CD8+ cytotoxic T cells, CD4+ helper T cells, CD45RO+ activated and memory T cells, and FOXP3+ regulatory T cells." (PMID 40240758, 2025). "As the proportion of lung Foxp3+CD4+ T cells in CD45+ cells positively correlated with day 21 tumor weight (data not shown), depletion of Foxp3+CD4+ T cells by anti-CD4 antibody likely has a stronger effect in augmenting the immune response for the >600 mg tumor than the 95–600 mg tumor group." (PMID 39835538, 2025). "Thus, the role of MSU-42011 in reducing FOXP3+ Tregs and increasing activated CD8+ T cells in the MPNST model is particularly intriguing, potentially alleviating immune suppression and enhancing anti-tumor immunity." (PMID 40563570, 2025). "This raises the possibility that the direct target genes regulated by Foxp3 are context-dependent, and that a differential requirement for Foxp3 may exist in TREG cells exposed to inflammatory environments, such as a tumor, compared to TREG cells residing in healthy organs." (PMID 40478934, 2025). "Additionally, combining Foxp3+ Treg depletion with non-ablative oligofractionated irradiation improved local tumor control and generated systemic immune responses in murine models of malignant mesothelioma." (PMID 41394821, 2025). "Among these cytokines, TNF could induce the CD4+CD25+FoxP3+Treg differentiation, CSF1 and CCL22 drive the differentiation of F4/80+CD11b+ monocytes to macrophages, and IL-23 inhibited CD8+T cell infiltration and promoted inflammation and tumor incidence." (PMID 41184283, 2025). "In addition, among patients with node-negative NSCLC (N0), tumor-infiltrating FOXP3+ Tregs were positively correlated with intratumor COX-2 expression and were associated with a worse recurrence-free survival." (PMID 38674427, 2024). "Furthermore, it is challenging to thoroughly assess how the targeted delivery of shRNA against FOXP3 stimulates lymphocyte cytotoxic activity in co-cultures with tumor cells compared to non-targeted delivery." (PMID 39772246, 2024). "We observed that in draining LNs (local immune response) and in the spleens (systemic immune response) of tumor bearing mice the expression of exhaustion markers in vivo had the same trend as expression of inflammatory cytokines, i.e. both were increased by ASO FOXP3 targeting of Tregs." (PMID 39234236, 2024). "Furthermore, biopsy results from another phase II trial, following treatment with a triple-mutated, third-generation oncolytic herpes simplex virus type 1, revealed an increase in tumor-infiltrating CD4+/CD8+ lymphocytes, while the count of Foxp3+ cells remained low." (PMID 39588306, 2024). "In addition to activation in tumor cells, STAT3 signaling is essential for the differentiation of Th17 cells, inhibition of dendritic cell maturation, and maintenance of the immunosuppressive function of Foxp3+ Treg cells." (PMID 38892375, 2024). "Once Tregs reach the tumor, differentiation/polarization and activation is induced by a variety of tumor- and immune-derived factors, including TGFβ, IL-10, PGE2/COX2, IL-35, adenosine, IL-6/STAT3, and even has_circ_0069313, a tumor-derived circular RNA that helps Tregs maintain FoxP3 levels." (PMID 38254801, 2024).
tumor (continued). "Furthermore, also relating to tumor immunity, several reports have shown that there are some subpopulations of Foxp3 + T cells with different functions, including non-Treg cells without an immunosuppressive function." (PMID 38402536, 2024). "Furthermore, we conducted an analysis of immunosuppressive cell populations, with a specific focus on Treg cells (CD4+Foxp3+ stained) and exhausted PD1+CD8+ T cells (PD1+CD8+ stained), utilizing multiplex immunofluorescence staining within the tumor microenvironments." (PMID 38163894, 2024). "As combination therapy could augment different cell types to improve anti-tumor immunity, we characterized CD8+, Tconv (CD4+Foxp3−), Tregs (CD4+Foxp3+), DCs (CD11c+MHC-II+), monocytic (CD11b+Ly6C+/−F480+/−CD64+/−) and neutrophilic (CD11b+Ly6G+) derived myeloid cell populations." (PMID 39343508, 2024). "In conclusion, the expression of FOXP3 in NSCLC is not uniform across all patients or tumor types." (PMID 38674427, 2024). "As for FoxP3+ T cells, the level of infiltration in the stroma area decreased significantly in responders (P = 0.048), but there was no significant reduction in total and tumor area in responders." (PMID 39313575, 2024). "Furthermore, recent studies have shown that PM_RCC presents unique immunological features, including a low intratumoral density of CD8+ and FOXP3+ lymphocytes and CD8+ T cells and fibroblasts as the most active incoming and outgoing components of the tumor microenvironment." (PMID 39768953, 2024). "Finally, a significant decrease in FoxP3 expression (p = 0.032) and an increase in signal transducer and activator of transcription 3 (STAT3) (p = 0.024) expression were measured in tumor-derived CD3+CD49− cells isolated from the metformin-treated group of mice." (PMID 38892058, 2024). "Analysis in CRC also shows a significantly higher frequency of CD4 + Foxp3 + Treg cells and CD68 + CD163 + M2 macrophages in intratumoral TLS compared to peritumoral TLS, suggesting a potential correlation between peri-tumor TLS and the immunosuppressive environment within the tumor." (PMID 39068459, 2024). "Finally, using IHC we found significant decrease in the number of FOXP3 expressing cells in all the Foxp3-ASO treatment arms in both the tumour and the spleen and an increase in TBET expressing cells in the tumour." (PMID 39578450, 2024). "In tumor lesions, FOXP3 expression seems to be almost absent." (PMID 38540417, 2024). "However, FOXP3-TILs represent a heterogeneous population, comprising not only suppressive subsets but also non-suppressive subsets with anti-tumor activity." (PMID 39267195, 2024). "Moreover, intraperitoneal injection of the compound in a syngeneic mouse tumor model led to decreased tumor growth in human PD-L-1 transfected murine melanoma and lung cancer, enhanced tumor infiltrating CD8+ cell abundance, and reduced tumor and FoxP3+ CD4+ cell abundance expressing PD-L-1." (PMID 38660299, 2024). "Moreover, the quantity of c-FOXP3+E-Cadherin− cells does not relate to tumor T stage but links to a lower degree of differentiation." (PMID 38047300, 2024). "However, we detected very few Foxp3–TdTomato+ or Foxp3+TdTomato+ Tregs in the MC38 TME, suggesting that gp96-null Tregs did not become ex-Tregs, but lost their ability to migrate into the tumor." (PMID 38787791, 2024). "In addition, the numbers of tumor infiltrated CD4+, CD8+, and Foxp3+ cells were evaluated by IHC." (PMID 39106430, 2024). "Furthermore, we assessed immune cell infiltration by quantifying several immune cell types involved in the tumor immune response, including Treg cells (CD4+Foxp3+ T cells), M1 macrophages (CD80+CD11c+ cells), M2 macrophages (CD80+CD206+ cells), PD-1+CD8+ cells, and CD39+CD8+ cells." (PMID 39465257, 2024).